CD8A (CD8 subunit alpha)
Diseases named in the same sentence as CD8A in open-access papers (continued):
Sharing a sentence is not in itself a finding about the gene and the disease.
tumor (continued). "However, our mouse model also allowed us to investigate TEG011_CD8α kinetics in the presence of tumor cells; and we observed sustained long-term TEG persistence mainly for γδTCR+CD4+CD8+ double-positive and a decline in γδTCR+CD8+ single-positive TEG011_CD8α cells." (PMID 34759930, 2021). "Importantly, CD8α:MyD88 costimulation functioned in a TCR-dependent but TLR ligand independent manner resulting in enhanced activity against weakly immunogenic or lowly expressed tumor antigens." (PMID 34344725, 2021). "Studies using highly immunogenic tumor models capable of producing spontaneous antitumor T cell activity revealed that type I IFN is essential for regulating the capacity of CD8α+ DCs to prime CD8+ T cells and facilitate subsequent immune-mediated antitumor responses." (PMID 33238631, 2020). "Additionally, we found that antitumor cytotoxic effector cells, such as CD8+ T cells and NK cells, as well as CD8α+ DCs (major antigen cross-presenting cells), were more abundant in the tumor-containing lungs of cisplatin-treated and irradiated Oasl1−/− mice than untreated Oasl1−/− mice." (PMID 31049360, 2019). "To further investigate whether PD-L1 amplification plays an independent role in regulating PD-L1 reactive expression, we ordered the samples by the expression of CD8A, and selected 70 tumor pairs having almost the same CD8A expression but different copy number status of PD-L1 (Figure." (PMID 31523194, 2019). "Thus, we investigated whether CD8α T cells and NK cells are involved in tumor growth inhibition in ApoE KO mice." (PMID 31275318, 2019). "We show that an elevated STAT1 transcriptional response is associated with a robust increase in GZMB (13-fold), CD8A (4.3-fold) and PD-L1 (2.6-fold) expression levels in STAT3Low tumours but not in STAT3High tumours (1.9-fold, 1.4-fold and 1.1-fold, respectively)." (PMID 28276425, 2017). "However, reductions in the proportions of CD8α+CD4- DCs extend beyond the tumor." (PMID 25886502, 2015). "Since clonal expansion of tumor antigen specific T cells induced by Ad-Flt3L-TK was inhibited by PC61 administration, we next determined whether PC61 affects the influx of CD4+ and CD8a+ T cells into the tumor, the draining lymph nodes and the spleen after treatment with Ad-Flt3L and Ad-TK." (PMID 18431473, 2008). "CD8a+ T cells were predominantly concentrated in the tumor centre, whereas CD206+ M2 macrophages were localized at the tumor periphery." (PMID 41141655, 2026). "We further quantified the spatial abundance of CD8a+ T cells, CD80+ M1 and CD206+ M2 macrophages in MTCQ1 tumors, which showed T cells located in the core of tumors and macrophages residing on tumor peripheries." (PMID 41141655, 2026). "Tumor sections were stained with antibodies recognizing α‐SMA, a marker for CAFs and CD8a, a marker for CD8+ T cells." (PMID 41257391, 2026). "Ex vivo tumor analysis revealed a significant reduction in CD8a+ T cells by day 3 post-EBRT, with the percentage area of CD8a+ T cells decreasing to 0.20 ± 0.17 %, compared to 0.91 ± 0.31 % in the CT-only control (P = 0.0126)." (PMID 41141655, 2026). "Mechanistically, 125I promoted CD8α+T cell infiltration, activated ICD-related pathways, and triggered systemic antitumor immunity, as demonstrated by inhibition of distant tumor growth in the bilateral tumor system." (PMID 41988184, 2026). "These panels include key markers, such as SOX10 for tumours, HLA-DR for antigen presentation and CD3/CD8a for T cell profiling, which are shared with the generated protein multiplex." (PMID 40842484, 2025). "In vivo labelling with fluorescent-tagged antibodies (B220, CD3, CD8a, CD68) in tandem with confocal microscopy allows for the identification of specific cell types (B cells, T cells and macrophages) in the tumour microenvironment (TME)." (PMID 39880930, 2025).
tumor (continued). "Prolonged recurrence-free survival, was associated with increased expression of T cell markers (CD4, CD8α, and PD-1) and elevated cleaved PARP levels in recurrent tumors, indicating enhanced anti-tumor immunity and apoptosis." (PMID 41208884, 2025). "For instance, several studies reported that Fe3O4 NPs covalently conjugated with tumor antigens can increase DCs uptake and induce their differentiation toward CD103+ or CD8α+ cross-presenting phenotypes, markedly enhancing CD8+ T cell activation efficiency." (PMID 41280655, 2025). "Despite the low baseline abundance of CD4+ and CD8α+ T cells in tumors (<1% of CD45+ cells), treatment with anti‐mPD‐1 mAb significantly delayed both tumor progression and recurrence." (PMID 41208884, 2025). "Six overlapping hub genes (CD8A, CDC20, E2F1, IL10, TNF, VCAM1) were overexpressed in GS 10 tumors, reflecting key pathways in tumor progression." (PMID 40227503, 2025). "Immunofluorescence staining of the tumor sections for CD8a and granzyme B (GZMB) revealed that codelivered immunomodulatory agents (iBINP) elicited a potent cytotoxic CD8+ T cell response." (PMID 41129257, 2025). "These included tumour markers (MelanA, S100, gp100, SOX10), immune markers (CD3, CD8a, CD20, CD16, CD31) and antigen-presentation markers (HLA-ABC, HLA-DR)." (PMID 40842484, 2025). "There was also a significant decrease in CD3e+PD-1+, CD8a+PD-1+, and CD4+PD-1+ T cells, as well as CD45+ cells in post- versus pre-ICI tumor samples (P < .05)." (PMID 38207230, 2024). "In the spleen of 4T1 tumor-bearing mice, the numbers/percentages of the lymphocytic subpopulations CD4+ and CD8α+ T-cells, B-cells, NK and NK-T cells significantly increased in response to chitin + anti-PD-1 combination treatment." (PMID 38605414, 2024). "We discovered that the lymphocyte infiltration and the expression of CD8A and CCL5 increased in tumor tissue after combination therapy." (PMID 39183447, 2024). "Research has shown that CD8A+ NKT-like cells not only possess cytotoxic granules, indicative of their potential to directly engage and destroy tumor cells, but also secrete high levels of interferon-gamma (IFN-γ) when stimulated by TCR-matched antigens." (PMID 38975339, 2024). "Specifically, the involvement of human leukocyte antigen (HLA) class I molecules (such as HLA‐A, HLA‐B, HLA‐C, HLA‐E and HLA‐F) and CD8A/B was consistently observed in the interactions between malignant cells and CD8 T cells in both tumour types." (PMID 39601163, 2024). "Immunophenotyping of matched pre- and post-ICI samples demonstrated significant decreases in intratumoral lymphocytes, CD3e+ and CD8a+ T cells, and PD-L1–PD1 engagement, as well as increased distance between tumor cells and CD8+PD-1+ T cells." (PMID 38207230, 2024). "The ratio and density of the CD8T_exhausted cells (CD8A+PD1+), Treg cells (FOXP3+), Treg_suppressive cells (FOXP3+PD1+), and malignant cells (CK+) in both total area and tumour area decreased in the OT sample." (PMID 39415331, 2024). "In the TME, CD8+ (CD8a+CD8b+) T cells are known to be differentiated from lymphocyte T cells (CD45+, CD3e+), and that has a key role in anti-tumor immunity." (PMID 39682244, 2024). "The markers used to characterize the immune and tumor compartments of the iTME were: CD3, CD4, CD8a, FOXP3, PD-1, PD-L1, CD68, CD33, and pan-keratin (PanCK)." (PMID 38898200, 2024). "We observed greater tumor infiltration of CD8+ T cells in the ExoPD2−low group than in the ExoPD2−high group, and this difference was prevented by treatment with the anti-CD8a antibody (P < 0.05)." (PMID 38755598, 2024). "CDC1, with CD8α + and/or CD103+ DCs as the main subsets cross-presents tumour antigens to CD8 + T-cells." (PMID 38890401, 2024). "We obtained whole-tumor transcriptomics data from the GSE78523 dataset and observed that the FOLR2 mRNA level was positively correlated with the CD8A mRNA level." (PMID 39702278, 2024).
tumor (continued). "CD8A, a marker of CD8 T cells, was only expressed in cluster 6, indicating the exclusion of anti-tumor immune cells from the tumor region." (PMID 38521868, 2024). "Previous studies have established a correlation between CD8A and the existence of CD8+ T cells, which exhibit anti-tumor activities, thereby suggesting more favorable immunotherapy outcomes." (PMID 39148731, 2024). "mIF on FFPE samples with antibodies of CD4, CD8α, FOXP3, Granzyme B, and pan CK were applied to analyze the tumor regions of pre- and post-ipilimumab treatment for 4 patients (P6, P7, P4 and P8)." (PMID 38448521, 2024). "In the example shown here, we visualized expression of Ecad, CD8a, and CD68, which are markers for epithelial and tumor cells, CD8+ T cells, and macrophages, respectively." (PMID 38172724, 2024). "The negative correlation between AXL and immune infiltration was further validated using multiplex immunofluorescence staining of AXL, CD8α, and CD103 in TKI-treated murine tumor tissues." (PMID 38310091, 2024). "CD8A, a glycoprotein mainly located on the surface of T lymphocytes, is downregulated in HCC and acts as a barrier against anti-tumor immunity." (PMID 37637055, 2023). "We found that the tumor growth kinetics, as well as the final tumor mass, between the Lm-LLO-ISG15 + anti-CD8α and PBS-treated animals were similar." (PMID 36831577, 2023). "We performed these experiments with well-differentiated mouse CD8α+ DCs supported by Flt3L, GM-CSF, SCF, and IL-4 in addition to pulsing by tumor cell lysates, which has turned out to be the most effective approach to produce CD141+ cDC1s." (PMID 36596856, 2023). "In pt115, the genes that were most upregulated in the expanded REP TIL clonotypes in the original tumor were NKG7, CCL5, and CD8A, but also those related to cytotoxicity, such as GZMB/H/K." (PMID 37484198, 2023). "Selected genes are reflecting main anti-tumor immune pathways, such as Th1 signaling (IFNG, TBX21, CD8A/B, IL12B, STAT1 and IRF1), Th1 chemoattraction (CXCL9, CXCL10 and CCL5) and cytotoxic functions (GNLY, PRF1, GZMA, GZMB and GZMH)." (PMID 37726776, 2023). "In preclinical models of immunogenic tumors, type I IFNs were essential for regulating the capacity of CD8α+ DCs to prime CD8+ T-cells and facilitate anti-tumor responses." (PMID 37173897, 2023). "RNAseq data from 60 tumor samples obtained prior to chemotherapy and also showed improved overall survival in patients with high PDCD1 and CD8A expression, median OS 20.5 vs 9.3 months (HR 0.475, p = 0.017)." (PMID 36781556, 2023). "On the other hand, NKT cells can stimulate the secretion of C-C motif chemokine ligand 17 (CCL17) by activating CD8α+ DC cells and attracting CD8+ cells to the tumor site." (PMID 37158883, 2023). "In keeping with that, the markers for anti-tumor immunity, including CD44 and CD8A were significantly reduced in the CDC20-high group." (PMID 37528490, 2023). "To trace the source of the exhausted PD-1high T cells, we cross compared PD-1+ CD8a+ CD45.1+ T cells in blood, tumor-draining lymph nodes, and tumor tissues." (PMID 37055410, 2023). "Significantly increased primary tumor staining for CD4, CD8α and NCR-1 as NK(-T) cell marker upon eMSC compared to sham treatment in all operated mice corroborated the flow cytometry results." (PMID 37928528, 2023). "Key markers of tumor immune response include TIL score, levels of cytotoxic (CD8α) T-cells, neutrophil or platelet to lymphocyte ratio (NLR/PLR)." (PMID 36809986, 2023). "To this end, we utilized immunohistochemistry with custom-made VisioPharm (Version 2018.4) analysis apps to determine the percent of total tumor area with immunoreactivity to CD68, CD3, CD4, CD8a, neutrophil elastase, and CD45r." (PMID 38136319, 2023). "cDCs can be further divided into two major subsets including CD8α+ and/or CD103+ cDC1s and CD11b+ cDC2s,132, 133 and both of them contribute to the immune response against tumor cells." (PMID 37829505, 2023).
tumor (continued). "Taken together, the ratio between CD8A and either C1QA, C1QB or C1QC in bulk tumour gene expression data is prognostic in at least five tumour types." (PMID 36724681, 2023). "Tumor progression was significantly suppressed in the MR16-1 group compared to the control and combined MR16-1 and CD8α depleting antibody groups." (PMID 36764954, 2023). "The bona fide candidate genes CD8A, CD4, and CD274 showed increased expression in T cells and tumor cells, respectively." (PMID 36672341, 2023). "NK cells (CD45+ CD3− CD8α+ CD16+ cells) represent 0.17 and 0.27% of immune cells in tumor lesions of pigs at R0 and R1 stages, respectively." (PMID 37526660, 2023). "Previous studies have shown that the average expression levels of CD8A, CD8B, GZMA, GZMB, and PRF1 can be used to estimate CTL levels in a tumor." (PMID 35588138, 2022). "LAG-3 expression was highly correlated with CD8A gene expression in the TCGA-SARC cohort and the predominant expression of LAG-3 by tumor-infiltrating CD8+ T cells was then confirmed by IHC." (PMID 36230502, 2022). "Taken together, these studies suggest that physiologic sources of HGFL support mammary tumorigenesis by promoting tumor cell proliferation, limiting tumor cell death, recruiting M2 (Arginase-1+) macrophages, and suppressing CD4+ and CD8a+ T cell recruitment." (PMID 35626096, 2022). "At the same time, our analysis found that PROZ was negatively correlated with genes related to immunotherapy efficacy such as CD8A, CD274 and GZMA, and was also negatively correlated with T-cell infiltration in tumor tissue." (PMID 36140703, 2022). "Spontaneous tumor antigen-specific T-cell priming is dependent on host type I IFN production, via a mechanism that involves the promotion of crosspresentation by CD8α+ DCs." (PMID 36496076, 2022). "IHC staining of tumor tissues from mice treated with B3GALT4 knockdown 9464D cells confirmed the expression levels of CXCL9 and CXCL10, and the percentage of CD8A-positive cells was increased after MβCD treatment, while caveolin-1 was decreased." (PMID 36284313, 2022). "A marked correlation between CD96/TIGIT messenger(m) RNA levels and CD3E/CD8a/CD4, with similar observations at the protein level (i.e., T cells), can be seen across multiple tumor types." (PMID 35812451, 2022). "Given the roles of CD8+ T cells in NB outcome, we analyzed the relationship between CD8A level and tumor stages and the prognosis of NB patients from the GSE49710 dataset." (PMID 36284313, 2022). "Patients that respond to PD-1 blockade also exhibited increased expression of STAT1, CXCL9, CXCL10, GZMB, CD8A, and CD8B, which is consistent with our observation in tumor model with IFNα-MSC treatment." (PMID 35145233, 2022). "These included genes consistent with pro-inflammatory immune responses (CD27, CD28, CD3e, CD8a, ICOS, ICOSLG, Pax5, TBX, GATA3, HLA-A, TNFSF14, GPR146), but also immune suppressive influences in the tumor immune microenvironment (CTLA-4, FoxP3, PD-1)." (PMID 36698398, 2022). "With correlating gene expression profiles of cytotoxic T lymphocyte (CTL) markers (CD8A, CD8B, GZMA, GZMB, and PRF1) with T-cell characteristics, the TIDE algorithm predicts immunotherapy of tumor patients." (PMID 36618968, 2022). "A positive correlation between GSDMD and CD8A, GZMB, and IFNG expression in CTLs was also seen in many other tumor types and in 30 primary tumor samples from patients with NSCLC, further confirming the associations seen from TCGA." (PMID 34429144, 2021). "We found that sorted tumor-infiltrating CD33high cells expressed high levels of CD33 gene, while lacked gene expression of CD3E, CD8A and NCAM1 (gene for CD56), compared to CD8+ T cells." (PMID 33000418, 2021). "In the correlation analysis of MB purity and the immune microenvironment, three genes related to immunity, namely, CD8A, CXCR2, and TNFRSF14, were negatively related to tumor purity." (PMID 34925437, 2021).
tumor (continued). "Collectively, these data present evidence that the antitumor response mediated by CD8α ALN-1 correlates with clonal expansion and increased TCR repertoire diversity in the TDLN and the tumor tissue, implying epitope spreading." (PMID 34772757, 2021). "In summary, CD8α ALN-1 promotes proliferation and effector functionality of antitumor CD8+ T cells and synergizes with CD13 AFR to mediate complete tumor eradication, allowing protection against secondary challenge." (PMID 34772757, 2021). "CD8α ALN-1 improves the efficacy of ATCT and synergizes with neovasculature-targeted TNF for full tumor eradication." (PMID 34772757, 2021). "When assessing cell type interactions between CD8+ T cells (marker gene: CD8A) and tumor cells (marker gene: EpCAM), most of them showed interactions known to be mediating immunity, including that of CD155 with CD96 between CD8+ T cells and tumor cells." (PMID 34417435, 2021). "This classification was based on expression of PD-L1 and recruitment of tumor-infiltrating lymphocytes (TIL), as evaluated by the expression of CD8A." (PMID 34638247, 2021). "Immunohistochemistry staining showed that SRE and anti-PD-1 antibodies increased CD8 (a marker of CD8+ T cells) and PRF1 granule exocytosis involved in cytotoxic T cell-mediated tumor cell death in the tumor tissues." (PMID 34659228, 2021). "Among these, 4 genes (CD8A, CD3E, CCL4 and ITGAL) were reported to have close relationship with tumor immune microenvironment and to be involved in various pathological processes of EC35–37." (PMID 34131259, 2021). "Collectively, treatment with CD8α ALN-1 stimulates host CD8+ T cells in the TDLN and tumor to acquire a favorable effector phenotype and execute effector functionality in response to TAA encounter." (PMID 34772757, 2021). "When segregating cells this way, 11.3% of all TILs co-expressed LAIR2 and CD4, while only 2.4% of TILs co-expressed LAIR2 and CD8A at log2(TPM + 1) > 4, indicating differences in LAIR2+ expression between different T cell compartments of the tumor samples." (PMID 35008369, 2021). "Based on the TIMER2.0, we found that six hub genes were significantly related to CD8A, CD8B, and PD-L1 in the LUAD and LUSC and most other tumor tissues in TCGA." (PMID 34422829, 2021). "Of the five GSDM gene members, only GSDMD expression showed a positive correlation with CD8+ T cell marker genes (e.g., CD8A, CD8B, PRF1, GZMA, GZMB, and IFNG) in CTLs across all three tumor cohorts." (PMID 34429144, 2021). "Nonetheless, treatment with CD8α ALN-1 massively increased CD8+ T cell expansion and shifted the naive/effector-ratio towards the latter in the TDLN and tumor." (PMID 34772757, 2021). "A CD8 T effector gene signature including CD8A, CD8B, EOMES, GZMA, GZMB, IFNG, and PRF1 was established to identify activated T cells and can be used to evaluate the abundance of CTLs in the tumor microenvironment." (PMID 33611641, 2021). "Both CD4+CD8α+ and CD4+CD8αβ+ TEG011 cells secreted significantly higher levels of IFNγ upon exposure to tumor targets than CD4+ TEG011 cells." (PMID 34759930, 2021). "For analyzing ESR2 expression level versus T cell infiltration in each tumor, the total expression of CD4, CD8α, GZMB (log2 counts per million) was used to assess the infiltration of cytotoxic T-lymphocytes, and correlations were computed vs ESR2 expression." (PMID 33462142, 2021). "We adjusted these results based on tumor purity, revealing strong and significant correlations between CD96 and CD8+ T cell markers (CD8A), general T cell markers (CD3D, CD3E, CD2), DC markers (HLA-DPB1, HLA-DRA, HLA-DPA1) in LGG." (PMID 33680972, 2021). "Given the overall TME scores of LUAD and LUSC patients, B cell, DC1, and six hub genes, like CD8A, CD8B, and PD-L1, were significantly positively correlated with stromal score and immune score and significantly negatively correlated with tumor purity." (PMID 34422829, 2021).